IL1B (interleukin 1 beta)
Diseases named in the same sentence as IL1B in open-access papers (continued):
Sharing a sentence is not in itself a finding about the gene and the disease.
tumor (continued). "These mediators influence all aspects of tumor growth and progression, providing a nurturing niche for cancer stem cells, and promoting angiogenesis, e.g., by IL-1β, dependently expressed vascular endothelial growth factor (VEGF), paving the way for metastasis, and taming adaptive immune response." (PMID 30042333, 2018). "The cytokine profile identified in the ACP RNA-Seq dataset, in particular the significantly higher expression of IL1A (18.1-fold), IL18 (14.8-fold), TNF (10.4-fold) and IL1B (7-fold) in human ACP tumours relative to controls, was suggestive of inflammasome activation [Suppl." (PMID 29541918, 2018). "Contrarily, IL-1β within the tumor microenvironment can promote carcinogenesis, tumor growth, and metastasis by different key mechanisms such as driving chronic non-resolved inflammation, endothelial cell activation, tumor angiogenesis, and the induction of immune-suppressive cells." (PMID 30042333, 2018). "In addition, tumor-derived IL-1β was shown to be essential for conversion of fibroblasts into cancer-associated fibroblasts, which expressed the immuno-suppressive receptors PD-L1 and PD-L2." (PMID 29983861, 2018). "Besides being characterized as NF-κB activating stimuli, IL-1β increase is known to play a key role in tumor growth, survival, invasion, and metastasis, while INF-γ is involved in the regulation of cancer stem cells (CSCs)." (PMID 29874851, 2018). "In a lung metastasis model, 2-DG decreased the IL-1β levels in the blood of tumor-bearing mice." (PMID 30586442, 2018). "Several studies have revealed different tumor-promoting effects of IL-1β." (PMID 29983861, 2018). "However, TAMs can also secrete pro-inflammatory cytokines, such as IL-1β, depending on the conditions in the tumor tissues." (PMID 30586442, 2018). "In conclusion, it was demonstrated that tumor-secreted factors could induce IL-1β maturation via the glucose-mediated signal activation of both NF-κB and mTOR in macrophages in the tumor microenvironment." (PMID 30586442, 2018). "Thus, to elucidate the mechanism of IL-1β production in macrophages stimulated by tumor-secreted factors, BMDMs were treated with B16F10-conditioned media in vitro." (PMID 30586442, 2018). "We could demonstrate that the cultured UCB γδ T cells were based on gene expression and efficient cytokine producers, especially with regard to IL-1β, IL-2, IL-8, and IL-15, and had a capacity for killing tumor cells comparable to cultured PB γδ T cells." (PMID 29707004, 2018). "Interestingly, we and others have shown that a number of anti-tumor therapeutics induces IL-1β production." (PMID 30042333, 2018). "Moreover, OSM expression in tumor lesions strongly correlated with that of IL-1β (Spearman rank correlation (r) = 0.7413) and IL-8 expression (r = 0.6937) and the expression of the two cytokines correlated with each other (r = 0.8970)." (PMID 30559930, 2018). "Moreover, APC-derived IL-1β promotes T cell-driven anti-tumor responses by favouring Tc1 and Th1/Th17 polarization, and by activating γδ T cells." (PMID 29983861, 2018). "Furthermore, IL-1β generated within the tumor microenvironment predominantly by tumor-infiltrating macrophages promotes tumor growth and metastasis via different mechanisms." (PMID 30042333, 2018). "IL-1β inhibition reduced tumor growth for an extended period." (PMID 30042333, 2018). "Finally, glucose inhibition by inoculation with 2-deoxy-D-glucose in vivo decreased the IL-1β levels in both the blood and tumor region of B16F10-bearing C57BL/6 mice relative to those in PBS-injected tumor-bearing mice." (PMID 30586442, 2018). "Based on these findings and our results showing that tumor cells upregulate IL1α and IL1β when in contact with macrophages, we hypothesized that increased IL1 expression could promote lung metastasis by activating the TAK1-P38 pathway." (PMID 29777109, 2018).
tumor (continued). "Compared to the macrophages in WT group samples, the macrophages isolated from PKN2-WT tumor showed significantly higher expression of Il1b, Tnf, Cxcl9, Il23, Ros1 and Il12b and significantly lower expression of Tgfb1, Vegfa, Egf, Retnla and Il10, illustrating predominant M1 phenotype." (PMID 29368606, 2018). "Therefore, it is necessary to clarify the production mechanism of IL-1β in the tumor microenvironment." (PMID 30586442, 2018). "IL-1β paves the way for tumor induction and growth as well as metastasis." (PMID 30042333, 2018). "Indeed, the consistent increase in brain IL-1β levels in tumor-bearing mice suggests a putative role for inflammasomes not only during chemotherapy, but also in cancer-induced depressive-like behavior." (PMID 29930550, 2018). "TLR stimulation can result in NF-κB-mediated survival and the expression of pro-inflammatory mediators (including IL-1β and TNFα) which may aid in tumour cell adherence, angiogenesis and metastasis." (PMID 29415982, 2018). "Because of the tight coupling between tumour cells and bone cells that occurs in bone metastases, the effects of IL-1B on the bone environment may also play important roles in this process." (PMID 29760166, 2018). "Although limited amounts of released active IL-1β cannot affect distant areas around tumor mass, it may have affected tumor mass itself as an autocrine signal or microenvironment to enhance its malignancy." (PMID 28430665, 2017). "Recent studies have reported that Th17 cells promote CTL proliferation and activation in tumor-bearing mice, and in some of these reports, Th17 cells that differentiated in the presence of IL-1β were also capable of promoting CTL induction to a greater extent than those in the presence of TGF-β." (PMID 29163524, 2017). "To further investigate the molecular mechanism underlying caspase-1-mediated tumoricidal effect, we first tested whether IL-1β and IL-18, two downstream cytokines of caspase-1 (refs 38, 39), contributed to PsV-induced tumour regression." (PMID 28397782, 2017). "In a Th1 microenvironment, proinflammatory cytokines (e.g., IL-6, IL-1α, and IL-1β) may contribute to tumour eradication by attracting leucocytes from the circulation and by increasing CD4 + T cell activity." (PMID 29089667, 2017). "Interestingly, intense IL-1β expression is observed in discrete cells within the tumor, mooted to be melanophages." (PMID 28450382, 2017). "Similarly in the antigen-specific antitumourmodel, we showed that deficiency of perforin in OT1 CTLs resulted in significantly reduced IL-1β level and consequently increased tumour size and weight." (PMID 28537251, 2017). "Conversely, in THP-1 cells, the decrease in IL-6 and IL-1β concentrations by CLE may diminish cytokine induced tumour immunosuppressive activity and cancer progression." (PMID 28764778, 2017). "Together suggest that IL-1β secreted from IRISOE tumor cells upregulates expression of its own receptor; IL-1R on the surface of naïve MSCs only, leading to activation of AKT, ERK, and p65/NF-κB signaling within MSCs, which leads to secretion of CXCL1 from MSCs." (PMID 29262555, 2017). "In both the in vitro tumor spheres and the in vivo murine model, there was a significant increase in the factors associated with M1 macrophage polarization, such as CCR5-binding chemokines (CCL3, CCL4, and CCL5), interleukins (IL-6 and IL-1β), and TNF-α." (PMID 28670313, 2017). "In contrast, the proinflammatory cytokines IL-6, IL-1α, and IL-1β may appear more unexpectedly as chronic inflammation related to the tumour." (PMID 29089667, 2017).
tumor (continued). "Therefore, we further analyzed the percentages of IL-17A-, IL-6-, IFN-γ-, IL-4-, granulocyte macrophage colony stimulating factor (GM-CSF)- and IL-1β-producing cells in tumor-infiltrating cell populations from mice administered L-4F or Sc-4F." (PMID 29245934, 2017). "IL-1β inhibits miR-101, a tumor-suppressive microRNA, via the COX-2-HIF1α pathway." (PMID 29113423, 2017). "To determinate whether IRF8 could impair the anti-tumour functions of Th9 cells differentiated with IL-1β, we used the same strategy." (PMID 29233972, 2017). "Both IL-1β and TNFα are present in the tumor microenvironment." (PMID 29113326, 2017). "Furthermore, STF reversed the effects of IL-1β on downregulation of various genes, such as, EBF3 associated with B lymphocyte differentiation, bone and neuronal genesis and tumor suppression." (PMID 28068976, 2017). "Other positive effects of TNF-α and IL-1β release stems from the fact that prior work from our laboratory demonstrated that both cytokines are necessary to restore the mixed lymphocyte reaction ability of DCs after phagocytosis of tumor irradiated cells." (PMID 29109725, 2017). "The OT1-mediated killing of target tumour cells in vivo induced IL-1β production through antigen presentation and NLRP3 inflammasome, indicating that the OVA tumour antigen was presented by APCs to activate OT1 T cells, and the CTLs then activated NLRP3 inflammasome in APCs." (PMID 28537251, 2017). "The ability of CLE to increase pro-inflammatory cytokines such as IL-1β in PBMC’s may aid in cancerous cell elimination through increased host anti-tumour activity." (PMID 28764778, 2017). "IL1B has been shown to play a significant role on tumor invasiveness and metastasis progression." (PMID 28143606, 2017). "Our findings further underscore the important role of glucose in tumour sphere-forming cells and provide a revolutionized view for glucose in the maintenance of tumour sphere-forming cells through activating and maintaining the expression of IL1α/IL1β and GCLM." (PMID 28300060, 2017). "The addition of IL-1-β to the endothelial monolayer significantly increased tumour cell migration." (PMID 28551814, 2017). "Notably, we experimentally demonstrate that maintenance of tumour sphere-forming cells are dependent on both IL1α/IL1β and cellular ROS homeostasis conveyed by GCLM, which are all glucose-inducible genes." (PMID 28300060, 2017). "Researches have confirmed that chemotherapy drugs could induce the production of NLRP3 inflammasome, activate the caspase-1 molecules and induce secretion of IL-1β, which can inhibit the anti-tumor effect of chemotherapy." (PMID 29312552, 2017). "During the tumor progression of myeloma within the bone marrow, indeed, both interleukin (IL)-1α and IL-1β secreted by MM cells stimulate the stroma to produce IL-6 through the linkage of the early growth response (EGR)-1 protein to the promoter of IL-6 (pIL6)." (PMID 28962646, 2017). "IL-1β is required for the polarization of CD8+ cytotoxic T-cells towards an anti-tumor response." (PMID 28428881, 2017). "Increased glycolysis promotes tumor-associated MDSC expansion in the NPC microenvironment by triggering the activation of p65 and the NLRP3 inflammasome signaling pathway, which leads to the production of IL-1β, IL6 and GM-CSF by malignant NPC cells." (PMID 28732079, 2017). "We postulated that TLR4 knockout prevents the increase in circulating cytokines that could stimulate muscle catabolism such as TNFα, IL-6 and IL-1β, and determined the effect of TLR4 deficiency on circulating cytokines in LLC tumor-bearing mice." (PMID 28536426, 2017). "Our results show that L-4F treatment significantly inhibited tumor progression, decreased inflammatory cell infiltration in tumor tissues, and reduced percentages of IL-17A-, IL-6-, GM-CSF- and IL-1β-producing cells to varying degrees in tumor tissues." (PMID 29245934, 2017). "IL1-β promotes tumor invasion and angiogenesis while it depresses antitumor immunity." (PMID 28966800, 2017).
tumor (continued). "Together suggest IRISOE enhances production/secretion of IL-1β in TNBC tumor cells under normal/normoxic, as well as hypoxic (e.g., within the aggressiveness niche in IRISOE TNBC tumors) conditions through stabilization of HIF-1α and/or activation of AKT, ERK and/or NF-κB signaling." (PMID 29262555, 2017). "On the other hand, IL-1β production from tumor cells may be considered a threat by the host's immune system." (PMID 28060744, 2017). "In C57BL/10J (TLR4+/+wild-type) and C57BL/6J (MyD88+/+wild-type) tumor-bearing mice, the tumor apoptosis rate, immune organ indexes and the levels of TNF-α, IL-1β and IL-6 in blood increased and the tumor weight decreased by oral administration of APS for 25 days." (PMID 28303957, 2017). "However, there was a significant effect of tumor cell type on IL-1β (H = 29.44, p < 0.0001), IL-6 (F2, 37 = 13.68, p < 0.0001), TNFα (F2, 38 = 26.73, p < 0.0001), and CXCL1 (H = 10.86, p < 0.005)." (PMID 28811490, 2017). "After treatment with cinobufagin, cinobufagin could up-regulate the expression of CRF and down-regulate the expression of IL-1β in plasma and tumor tissues homogenate than the model group mice." (PMID 28002791, 2017). "For example, exposure of non–tumor-bearing mice to paclitaxel induced IL-1b production." (PMID 28968987, 2017). "The transcription factor NFκB was activated by IL-1 receptor to promote tumor development, and the application of IL-1β neutralizing antibodies could significantly inhibit tumorigenesis and development." (PMID 29312552, 2017). "Moreover, if the BF-rTK survived in the tumor via IV administration, it would be assumed that BF-rTK stimulated the production of higher concentrations of cytokines (e.g., IL-1α, IL-1β, IL-2, IL-10, IL-17, GM-CSF, and MCP-1)." (PMID 27275821, 2016). "Therefore, recruited inflammatory cells in vivo would provide IL-1β or equivalent signals in the tumor microenvironment to induce hormone-independent tumorigenesis." (PMID 27609180, 2016). "However, further molecular and animal experiments are needed to test that inflammasome/IL-1β-induced CCL2 regulates the recruitment of macrophages in tumor microenvironments and metastatic sites." (PMID 27786298, 2016). "Interestingly, we found that low dose 5-FU (10 mg/kg) did not induce inflammasome activation in MDSCs leading to induction of IL-1β compared with high dose (50 mg/kg) in the same tumor-bearing mouse model." (PMID 27027355, 2016). "IL-1α and IL-1β can be produced by tumor as well as stromal cells." (PMID 27630452, 2016). "The potent anti-inflammatory and anti-tumor effects of embelin were demonstrated by the findings that this agent dramatically reduced the infiltration of macrophages and decreased the expression of TNFα, IL-6, IL-1β, COX-2 and iNOS in colonic tissues." (PMID 26799669, 2016). "IL-1β and TGF-β cooperatively upregulate stemness-associated genes, including NESTIN, BMI-1, NOTCH-2, and LIF in glioma cells, thereby increasing invasiveness, drug resistance, and tumor growth in vivo." (PMID 28116318, 2016). "In contrast, lung tissues from tumor-bearing caspse-1 KO mice produced less mature IL-1β protein." (PMID 27786298, 2016). "IL-1β is an important factor for tumor angiogenesis and for stimulation of tumor invasiveness." (PMID 27807511, 2016). "We found elevated concentration of IL-1β in tumor microenvironments from WT mice." (PMID 27786298, 2016). "TNF-α and IL-1β are released into the tumor environment when TLRs are activated in tumor cells." (PMID 28116318, 2016).
tumor (continued). "In order to provide mechanistic insights into the IL1β response to estrogens within the tumor microenvironment, we began our study determining that IL1β is one of the most induced genes by ligand-activated GPER, as assessed in a nanostring analysis performed in CAFs (data not shown)." (PMID 27072893, 2016). "It was reported that IL-1β and IL-6 stimulate glucose metabolism and promote tumour progression." (PMID 26869854, 2016). "IL1B transcripts are increased in tumor biopsies of patients with metastatic CRC and polymorphisms in IL-1 receptor antagonist (IL-1RA) (encoded by IL1RN) may be associated with CRC." (PMID 27148488, 2016). "However, further studies are needed regarding the unique function of each IL-1 family protein, including IL-1α, IL-1β, and IL-18, in the tumor development." (PMID 27786298, 2016). "Besides, IL-1β promotes malignant transformation and tumor aggressiveness in oral cancer, indicating its tumorigenic role." (PMID 27811377, 2016). "However, clinical chickens with neoplasms showed IL-6, IL-1β and IFN-β levels that were significantly altered within the clinical group." (PMID 27252695, 2016). "Additionally, increment of IL-1β in TME can lead to stabilization of HIF-1 in tumor cells and contribute to tumorigenesis through activation of genes implicated in metabolism, angiogenesis, and migration." (PMID 27630452, 2016). "Future studies should address whether cytokines or growth factors such as TGF-β1, PDGF and IL-1β in the tumor environment contribute to activating quiescent fibroblasts." (PMID 27884164, 2016). "Toll-like receptor engagement could also be involved in IL-1β induction, with induction of primary necrosis and haemorrhage in the tumour (evident after ingenol mebutate treatment in mice) potentially providing self-derived Toll-like receptor agonists." (PMID 27100888, 2016). "In particular, the activation of NLRP3 inflammasome via TLR4 signalling led to IL-1β release after caspase-1 activation, whereas, the activation of caspase-11 was important for both IL-1α release and NLRP3-dependent IL-1β release in the lung of tumor-bearing mice." (PMID 27528423, 2016). "The keratinocyte-derived IL-1α may be involved in (MyD88-dependent) induction of IL-1β, with IL-1β induction by IL-1 reported previously and tumour-derived IL-1β also shown to recruit neutrophils to the tumour." (PMID 27100888, 2016). "Both IL-1β and IL-33 were abundantly present in P29 tumours." (PMID 26775708, 2016). "In the current study we provide new findings on the networks that control the inflammatory phenotype of CAFs and MSCs, demonstrating key roles for the inflammatory cytokines TNF-α and IL-1β in upregulating the release of inflammatory, tumor-promoting chemokines by these two cell types." (PMID 25928089, 2015). "Enhanced stemness of cancer cells by cytokines (e.g. TGF-β and IL-1β) from TAMs may contribute to the pro-tumor activities of TAMs." (PMID 26359357, 2015). "Several studies clearly demonstrated the relevance of IL-1β in tumor development and metastasis." (PMID 26696754, 2015). "Our data revealed that the outcome of MSC–tumor interaction is dependent on the nature rather than the type of tumor cells and that epithelial cadherin type 1 (CDH1) and IL-1β expression by tumor cells are key factors in determining the outcome of hMSC–tumor cross-talk." (PMID 26204886, 2015). "Further analysis of excised intestinal polyps showed that the adoptive transfer of Apc HET Tregs reduced the levels of proinflammatory mediators IL-6, IL-1β, and IL-23 in the tumor microenvironment compared with wild type intestinal tissue but the expression level of TNF was not decreased." (PMID 26146642, 2015). "In addition, we showed that OSCC cell lines secrete a substantial amount of IL-1β, which promotes tumor proliferation in an autocrine manner." (PMID 26462152, 2015).